FBXW7 (F-box and WD repeat domain containing 7)
Diseases named in the same sentence as FBXW7 in open-access papers (continued):
Sharing a sentence is not in itself a finding about the gene and the disease.
prostate carcinoma (18 papers, 2012 to 2025). A carcinoma that arises from epithelial cells of the prostate gland. "Depletion of FBXW7 abrogated inhibition of cell proliferation caused by upregulation of FER1L4 in prostate cancer cells, indicating that FER1L4 exerted antitumor activities via miR-92a-3p/FBXW7 axis." (PMID 35928868, 2022). "Silencing of FBXW7 reversed the cell phenotypes caused by FER1L4 overexpression in prostate cancer cells." (PMID 32140077, 2020). "In addition, we also identified mutations of FBXW7 in prostate cancers (5.6%), kidney cancers (16.7%), and bladder cancers (18.8%)." (PMID 23166673, 2012). "Depletion of FBXW7 abolished the cell proliferation inhibition caused by FER1L4 upregulation in prostate cancer cells, indicating that FER1L4 exerts antitumor activity through the miR-92a3p/FBXW7 axis." (PMID 40534867, 2025). "Upregulation of FER1L4 reduced proliferation and increased apoptosis of prostate cancer cells by sponging miR-92a-3p and upregulating FBXW7." (PMID 40534867, 2025). "Previous studies showed that the down-regulated expression of FBXW7 by 3D spheroid formation suppressed the protein degradation of KCa1.1 in human prostate cancer LNCaP cells, which increased KCa1.1 activity." (PMID 38892210, 2024). "In the present study, we found that the transcriptional activity of FBXW7 was promoted by the inhibition of the Ca2+-activated K+ channel, KCa1.1, in a 3D spheroid model of human prostate cancer LNCaP cells through the Akt-Nrf2 signaling pathway." (PMID 38892210, 2024). "The data demonstrated that the FER1L4/miR-92a-3p/FBXW7 axis controlled the key signaling pathway in prostate cancer cells." (PMID 32140077, 2020). "Immunohistochemical staining showed that LSD1 and FBXW7 proteins are both mainly localized in nuclei of luminal cells of prostate carcinoma cells." (PMID 33708617, 2020). "Our work provided new understandings for the regulation of YAP1 signaling by FER1L4/miR-92a-3p/FBXW7 axis in prostate cancer." (PMID 32140077, 2020). "The results revealed that FER1L4 control prostate cancer proliferation and apoptosis via upregulation of FBXW7 and downregulation of YAP1 and its target gene expression." (PMID 32140077, 2020). "Previous study revealed that the expression of FBXW7 protein in prostate cancer was markedly reduced compared with normal tissues." (PMID 33708617, 2020). "In previous reports, LSD1 is highly expressed in various type of prostate cancer while the expression of FBXW7 decreased in prostate cancer." (PMID 33708617, 2020). "We demonstrate that LSD1 can promote the survival of prostate cancer cells by down-regulating FBXW7 protein levels." (PMID 33708617, 2020). "We found that the 110 and 70 kDa bands were indeed reduced following the treatment with FBXW7 siRNA in the two prostate cancer cell lines." (PMID 27253416, 2016). "We used the same antibody to verify the size of endogenous FBXW7 isoforms in FBXW7 siRNA-treated prostate cancer cell lines." (PMID 27253416, 2016). "In prostate cancer, up-regulated FBXW7 also suppresses the expressions of c-Myc and Notch-1." (PMID 38892210, 2024). "In addition, FBXW7 plays an important role in the modification of sensitivity to anti-cancer drugs in cancers, including prostate cancer." (PMID 38892210, 2024). "Therefore, FBXW7 should be an independent factor that affects the survival of prostate cancer cells." (PMID 33708617, 2020). "Additionally, the expression of FBXW7 was positively correlated with FER1L4 in prostate cancer tissues." (PMID 32140077, 2020). "FBXW7 also played a tumor suppressor role in prostate cancer cells." (PMID 32140077, 2020). "In conclusion, the study demonstrated a FER1L4/miR-92a-3p/FBXW7 axis in prostate cancer." (PMID 32140077, 2020). "FBXW7 was downregulated and suppressed several cancer progression including prostate cancer." (PMID 32140077, 2020).
prostate carcinoma (continued). "Thus, the current study revealed a FER1L4/miR-92a-3p/FBXW7 axis in prostate cancer." (PMID 32140077, 2020). "As a positive regulator of FBXW7, we found that FER1L4 decreased stability of YAP1 protein to reduce its expression in prostate cancer cells." (PMID 32140077, 2020). "Interestingly, in PC-3 and DU145 cells, we also observed that FER1L4 overexpression decreased the phosphorylation of AKT protein which was reversed towards FBXW7 silencing, indicating PI3K/AKT signaling was also regulated by FER1L4/FBXW7 in prostate cancer cells." (PMID 32140077, 2020). "Interestingly, we detected an association between patient survival and gene expression of USP9X only, but not of HUWE1, BTRC, and FBXW7, even though all gene products are able to interact with Mcl-1, further emphasizing the role of the deubiquitinase in prostate cancer progression." (PMID 37173959, 2023). "However, the interaction between LSD1 and FBXW7 has not been reported in prostate cancer." (PMID 33708617, 2020).
non-small cell lung carcinoma (17 papers, 2015 to 2024). A group of at least three distinct histological types of lung cancer, including non-small cell squamous cell carcinoma, adenocarcinoma, and large cell carcinoma. "In support to this, in vitro and in vivo silencing of FBXW7 in non-small cell lung cancer (NSCLC) can significantly trigger EMT, promote migration and invasion and confer resistance to gefitinib treatment." (PMID 30791487, 2019). "Recently, it has also been found that miR-182 increased the proliferation of non-small cell lung cancer cells by suppressing FBXW7." (PMID 30791487, 2019). "Studies have indicated that non-small cell lung cancer (NSCLC) cells with low expression of FBXW7, such as NCI-H1299 cells, exhibited mesenchymal phenotype and are more resistant to cisplatin than cells with an epithelial phenotype." (PMID 30791487, 2019). "Previous study in non-small cell lung cancer has reported that FBXW7 is a downstream target of miR-367." (PMID 28716020, 2017). "miR-182 increases the proliferation of non-small cell lung cancer cells by inhibiting FBXW7." (PMID 37047300, 2023). "Besides, FBXW7 had been confirmed as a target of miR-367 in non-small cell lung cancer, and could suppress EMT progression of HCC cells." (PMID 28716020, 2017). "In non-small cell lung cancer, CDK8/FBXW7-mediated NICD1 degradation can be competitively abolished by RFC4 (a DNA replication factor), which results in increased NICD1 stability and promotes NSCLC invasiveness." (PMID 38606172, 2024). "Research revealed that silencing the FBXW7 gene can promote the development of EMT and confer resistance to sorafenib and cisplatin in non-small cell lung cancer (NSCLC)." (PMID 38027013, 2023). "For instance, FBXW7 can suppress cell migration and invasion by negatively regulating the transcription factor SNAIL in human non-small cell lung cancer (NSCLC)." (PMID 33800394, 2021).
osteosarcoma (16 papers, 2016 to 2025). A usually aggressive malignant bone-forming mesenchymal neoplasm, predominantly affecting adolescents and young adults. "FBXW7 has been identified as a tumor suppressor also in osteosarcoma and its high expression has been related to better patient survival, while in osteosarcoma cell lines the overexpression of FBXW7 causes apoptosis induction and growth arrest." (PMID 38534381, 2024). "In osteosarcoma tissues, it has been shown that FBXW7 is downregulated compared to normal bone tissues." (PMID 30791487, 2019). "Furthermore, microRNA‐92a was shown to directly bind to FBXW7 and, in turn, repress the expression of FBXW7, thus triggering the tumour growth in osteosarcoma." (PMID 32394588, 2020). "Moreover, in vitro and in vivo overexpression of FBXW7 in osteosarcoma strikingly instigated apoptosis and inhibited tumor progression via the degradation of c-Myc and cyclin E." (PMID 30791487, 2019). "miR-92a-3p promotes tumour growth and reduces apoptosis by suppressing FBXW7 in osteosarcoma." (PMID 29552296, 2018). "LncRNA GClnc1 facilitated the progression of osteosarcoma by stabilizing NONO through inhibiting FBXW7-mediated ubiquitination." (PMID 40641925, 2025). "In osteosarcoma, the lncRNA GClnc1 facilitates tumor progression by stabilizing NONO and preventing FBXW7-mediated ubiquitination, whereas targeting miR-27a−3p can restore FBXW7 expression to sensitize Taxol−resistant cells." (PMID 40370434, 2025). "For example, FBXW7 (involved, as we have seen in this review, in mTOR and HIF ubiquitination) could be at the center of an activation strategy in osteosarcoma." (PMID 38534381, 2024). "Therefore, the PLK1/FBXW7/Myc axis creates a positive auto-regulatory signal crucial in promoting tumorigenesis and underscores PLK1 as potential therapeutic target in Myc-overexpressing tumors, as validated in our previous study on osteosarcoma cell lines." (PMID 38791684, 2024). "Thus, it is possible that flavopiridol-mediated up-regulation of FBXW7 may be, at least in part, responsible for the decrease in MCL-1 protein levels observed in some osteosarcoma cell lines." (PMID 29805751, 2018).
adenoma (15 papers, 2012 to 2025). A neoplasm arising from the epithelium. "Four FBXW7 mutations were discovered, one in a flat adenoma (c.1394G>A (p.R465H)) and three in polypoid adenomas, namely c.832C>T (p.R278*), and two times c.1513C>T (p.R505C)." (PMID 22848674, 2012). "Although we found that FBXW7 which encodes E3 ubiquitin-ligase enzyme is mutated only in colorectal adenocarcinomas, previous report has identified somatic mutations in FBXW7 in adenomas." (PMID 23301059, 2013). "Truncating mutations were also validated in SCUBE2, RELN, FBXW7, MLL3, WTX/FAM123B, OTUD7B and KPRP across the MAP and FAP adenomas." (PMID 26414517, 2016). "FBXW7 loss promotes intestinal tumorigenesis by enhancing proliferation, disrupting differentiation, causing DEK accumulation, altering TPM splicing, and accelerating adenomas with APC deficiency." (PMID 41373479, 2025). "Genomic analysis of APC-driven adenomas and adjacent mucosa of FAP patients revealed that the tissue adjacent to the adenoma site carries 23% of the somatic mutations and genomic variations in known cancer driver genes, which are often detected in adenomas (i.e., APC, K-RAS, FBXW7, TCFL2)." (PMID 39594797, 2024). "Analysis of the common insertion sites for transposon in neoplasms, adenomas and adenocarcinomas revealed that 80% of insertions fell in known CRC genes including APC, FBXW7 (F‐box and WD repeat domain containing 7), PTEN (phosphatase and tensin homolog), and SMAD4, thus validating the approach." (PMID 26115037, 2015). "Elevated levels of two particular Fbxw7 substrates, Klf5 and Tgif1, were found in normal intestine and adenomas of R482Q/+, R482Q/R482Q and Fbxw7−/− mice, but not Fbxw7+/− animals." (PMID 23676439, 2014).
esophageal squamous cell carcinoma (14 papers, 2012 to 2026). Esophageal squamous cell carcinoma (ESCC) is a type of esophageal carcinoma (EC) that can affect any part of the esophagus, but is usually located in the upper or middle third. "Loss of FBXW7 promotes esophageal squamous cell carcinoma (ESCC) progression by enhancing ANXA2 to activate the MAPK pathway." (PMID 38688909, 2024). "A study determined that FBXW7 deficiency and certain FBXW7 mutations can promote the invasive and migratory capacity of esophageal squamous cell carcinoma (ESCC) cells via MAP4 overexpression and ERK phosphorylation." (PMID 38027013, 2023). "Conversely, K48/K11-linked ubiquitin chains assembled by FBXW7 or TRIM65 target ANXA2 for 26S proteasomal degradation, leading to protein loss in FBXW7-deficient esophageal squamous cell carcinoma and conferring chemoresistance by upregulating MAPK signaling." (PMID 41185558, 2025). "In esophageal squamous cell carcinoma, the overexpression of miR-223 was found to promote tumor progression by inhibiting FBXW7-mediated regulation of the cell cycle." (PMID 32577098, 2020). "In esophageal squamous cell carcinoma (ESCC), loss of FBXW7 expression has been indicated due to genetic alteration." (PMID 30791487, 2019). "By inhibiting FBXW7, miR-27a-3p enhances esophageal squamous cell carcinoma cell growth." (PMID 39823500, 2025). "Our current findings disclosed a novel FBXW7/MAP4/ERK axis in esophageal squamous cell carcinoma." (PMID 36991467, 2023). "FBXW7 mRNA expression is reduced in esophageal squamous cell carcinoma (ESCC)." (PMID 30086763, 2018). "The aim of this study was to clarify the clinical significance of miR-223 and FBXW7 in oesophageal squamous cell carcinoma (ESCC) patients, and to elucidate the mechanism by which FBXW7 is regulated by miR-223." (PMID 22108521, 2012).
diffuse large B-cell lymphoma (13 papers, 2017 to 2025). "Consistently, another study demonstrated that low expression of CREBBP or EP300 inhibits H3K27 acetylation via the FBXW7–NOTCH–CCL2/CSF1 axis to induce the polarisation of tumour-associated macrophages to the M2 phenotype and tumour cell progression in diffuse large B-cell lymphoma (DLBCL)." (PMID 38493218, 2024). "In diffuse large B-cell lymphoma (DLBCL), KMT2D mutations promote the migration of Treg cells into the tumor microenvironment and suppress immune responses through the FBXW7-NOTCH-MYC/TGF-β1 signaling axis, thereby promoting tumor growth." (PMID 41372946, 2025).
endometrial cancer (13 papers, 2010 to 2025). Primary or metastatic malignant neoplasm involving the endometrium (mucous membrane that lines the endometrial cavity). "The Wnt pathway is known to induce the EMT transcription factor, Snai2, and it would thus be expected that mutations in FBXW7 alone would be sufficient to drive tumor formation; however, this study revealed that endometrial cancers were highly penetrant only when PTEN was deleted." (PMID 37587857, 2023). "Given that FBXW7 missense (but not truncating) mutations are common in normal endometrial glands and that its substrates appear to vary by tissue, addressing these is critical if FBXW7 is to be a target for endometrial cancer prevention and therapy." (PMID 37589076, 2023). "Taking an agnostic approach, we identified enrichment of a gene signature corresponding to the Wnt pathway effector LEF1 in Fbxw7 mutant mouse endometrial cancers." (PMID 37589076, 2023). "A further common area was detected on chromosome 4q32.1 between the nucleotide location 153,242,171 and 153,271,571 (29.4 kb) and covering FBXW7 gene in 63% (41/65) of examined endometrial carcinoma." (PMID 36625073, 2023). "TP63+ squamous differentiation in invasive endometrial cancer was also recently reported in a subset of Fbxw7/Pten knockout mice." (PMID 34941867, 2021). "Spearman’s correlation analysis further proved that the expression of FBXW7 correlated negatively with STYX in endometrial cancer tissues." (PMID 32239181, 2020). "Generally speaking, all of our results demonstrated that STYX/FBXW7 axis participates in the development of endometrial cancer cell via Notch–mTOR signaling pathway." (PMID 32239181, 2020). "Taking these observations together with our data, it appears plausible that failure of Fbxw7 missense‐mutant endometrial cancers to degrade Lef1 may contribute to tumorigenesis and EMT in our GEMM." (PMID 37589076, 2023). "By transcriptomic analysis, we identify LEF1 signalling as upregulated in Fbxw7/FBXW7‐mutant mouse and human endometrial cancers, and in human isogenic cell lines carrying FBXW7 mutation, and validate LEF1 and the additional Wnt pathway effector TCF7L2 as novel FBXW7 substrates." (PMID 37589076, 2023). "The major pathways involved in endometrial cancer seem to be PI3K/Akt/mTOR, MAPK, WNT, and FBXW7 signaling." (PMID 33546293, 2021). "A lower FBXW7 expression and a higher expression of STYX were observed in human endometrial cancer tissues." (PMID 32239181, 2020). "We also examined the expression level of FBXW7 and STYX in endometrial cancer cell lines." (PMID 32239181, 2020).
cholangiocarcinoma (12 papers, 2010 to 2025). A carcinoma that arises from the intrahepatic biliary tree (intrahepatic cholangiocarcinoma) or from the junction, or adjacent to the junction, of the right and left hepatic ducts (hilar cholangiocarcinoma). "Moreover, deficiency of FBXW7 was found to induce metastasis in cholangiocarcinoma cells via promoting EMT in vitro and in vivo." (PMID 30791487, 2019). "Of note, among these targets, FBXW7 has been found to suppress the epithelial–mesenchymal transition, stemness and metastatic potential of cholangiocarcinoma cells." (PMID 31443224, 2019). "While FBXW7 mutations are found in several diverse human cancer types such as T-ALL, cholangiocarcinoma, stomach, colon, pancreas, and endometrium, they are rare in other cancers." (PMID 25669969, 2015). "Interestingly, FBXW7 decreased the p-AKT level in some cholangiocarcinoma cell lines, whereas the dominant-negative form of FBXW7 (FBXW7-ΔF-box) significantly upregulated the p-AKT level." (PMID 40083925, 2025). "The role of FBXW7 in cholangiocarcinoma and other gastrointestinal cancers." (PMID 39749199, 2024). "Growth and progression of cholangiocarcinoma cells can also be regulated by FBXW7." (PMID 32226545, 2020). "Thus, FBXW7 expression has potential as an independent prognostic marker for cholangiocarcinoma." (PMID 30791487, 2019). "ZEB1, serving as a transcription factor promoting the EMT process, is associated with the stem-like properties of cholangiocarcinoma (CCA) cells, which can be explained by the fact that FBXW7 dampens EMT and stemness of CCA cells via the mTOR/ZEB1 signaling pathway." (PMID 35515121, 2022). "The ubiquitin ligase FBXW7, a general tumor suppressor in human cancer, has been implicated in diverse cellular processes, however, its role in cholangiocarcinoma (CCA) metastasis has not been identified." (PMID 25749036, 2015). "Similarly, lack of FBXW7 expression induces upregulation of MCL-1 in cholangiocarcinoma, resulting in resistance to cisplatin." (PMID 36998461, 2023).